APP (amyloid beta precursor protein)
Diseases named in the same sentence as APP in open-access papers (continued):
Sharing a sentence is not in itself a finding about the gene and the disease.
Senile plaques (141 papers, 2004 to 2025). Senile plaques are extracellular deposits of amyloid in the gray matter of the brain. "The J9 model is a transgenic mouse that expresses human amyloid precursor protein (APP) with Swedish (K670N/M671L) and Indiana (V717F) mutations, which increases Aß formation and favors Aß42, the form more likely to be found in senile plaques." (PMID 37333297, 2023). "In unusual conditions, i.e., some mutations of APP gene, such as the Lys670Asn/Met671Leu (Swedish mutation), APP is prone to be processed by the β pathway, resulting in an excessive accumulation of insoluble Aβ and eventually the development of senile plaques." (PMID 34527172, 2021). "In line with our results, both astrocytes associated with senile plaques in APP/PS1 mice and astrocytes from APPSwe mice in an early stage of the disease display atypical Ca2+ waves." (PMID 33396295, 2020). "Our data have revealed that SCF+G-CSF treatment reduces diffuse and fibrillar Aβ deposits, increases the association of microglia/macrophages with senile plaques, and enhances Aβ uptake by microglia/macrophages in the brains of aged APP/PS1 mice." (PMID 33269098, 2020). "Elevated APP expression is also associated with gliosis and is the main component of the senile plaques; Alzheimer’s pathology is present in about half of all cases of GBM." (PMID 27770278, 2017). "In DS, the postmortem findings of senile plaques and neurofibrillary plaques (NFTs) is assumed to be caused by the overexpression of the amyloid precursor protein (APP) following triplication of chromosome 21 and accumulation of beta-amyloid." (PMID 27330841, 2016). "It is known that lipids are tightly connected with metabolism of the Amyloid Precursor Protein (APP), which produces Amyloid-beta peptide (Aβ), the main component of senile plaques, which represent the main pathological hallmark of AD." (PMID 23306153, 2013). "Similarlythe major protein component of senile plaques is a 4.2 kDa polypeptidetermed Aβ, which is derived from a larger precursor (APP) encoded onchromosome 21." (PMID 19946466, 2009). "These mutations adversely affect APP processing and result in the increased production of insoluble Aβ, which is deposited in the form of senile plaques." (PMID 19578515, 2008). "Additionally, neurons exhibiting PANTHOS are identified as the primary source of senile plaques in APP-associated AD models." (PMID 39000011, 2024). "These senile plaques are accumulations of fibrils and aggregations of Aβ located outside of cells caused by abnormal proteolytic degradation of the amyloid precursor protein (APP), which is enhanced by presenilin-1 (PS1)." (PMID 37744008, 2023). "Accordingly, the aim of the current investigation was to evaluate the effects of low doses of fluoride on the brains of mice carrying the APP/PS1 mutation, focusing on senile plaques, the enzymes that cleave APP, synaptic proteins, oxidative stress, and learning and memory." (PMID 31010414, 2019). "In addition, to regulate glucose homeostasis, insulin has also been found to play a major role in regulating APP and its derivative Aβ protein associated with senile plaques, a neuropathological hallmark of AD." (PMID 30759846, 2019). "APP is a precursor of Aβ-peptides and is cleaved by two enzymes (β- and γ-secretases), which are essential steps for generating pathogenic Aβ peptides (a central component of senile plaques in AD brains)." (PMID 28337142, 2017). "As described in the introduction, senile plaques, a neuropathological hallmark of AD, are made up largely of 38-43 amino acid β-amyloid peptides (Aβ), which are liberated from a larger integral membrane protein, amyloid precursor protein (APP), by sequential β- and γ-secretase cleavage." (PMID 22192775, 2011). "On the other hand, calsyntenin-1 and APP have been found to be colocalized in the dystrophic neurites and senile plaques of AD brain specimens, and furthermore, some calsyntenin-1-containing vesicles also contain the APP protein." (PMID 39000564, 2024).
Senile plaques (continued). "Solid forms of senile plaques were detected in APP knock‐in mice after formic acid treatment with Davidson's and Bouin's fluid fixative as the brain of AD patients." (PMID 36879381, 2023). "The main component of senile plaques is the Aβ peptide, which is derived from the breakdown of amyloid precursor protein (APP)." (PMID 36902671, 2023). "AD involves Aβ, which is the major component of senile plaques, produced due to the sequential action of β- and γ-secretases on the amyloid precursor protein (APP) through the amyloidogenic cleavage pathway." (PMID 37108480, 2023). "Compounds of this type have been developed as potential AD therapeutics due to the role of BACE1 in APP cleavage and generation of the Aβ peptides found in senile plaques." (PMID 37269953, 2023). "The most striking phenomenon, however, is that GBRs stabilize APP in complexes at the cell surface and reduce the proteolysis of APP to Aβ, the latter serving as the critical step in the formation of senile plaques in AD patients." (PMID 35408817, 2022). "BIN1 directly interacts with RIN3 to initiate RAB5-mediated endocytosis, which is essential for β-secretase (BACE1)-mediated β-secretase cleavage of β-amyloid precursor protein (APP) to generate Amyloid-β (Aβ), the key component of senile plaques in AD." (PMID 35241726, 2022). "Amyloid precursor protein (APP) and amyloid‐β (Aβ) peptides are central to the generation of senile plaques in AD." (PMID 35076977, 2022). "HLJDD reduced the destruction of hippocampal nerve cells and the formation of senile plaques in APP/PS1 mice." (PMID 36506569, 2022). "The results showed that the number of senile plaques in the cerebral cortex and hippocampus of APP/PS1 transgenic mice in the melatonin intervention group was significantly reduced compared with that of APP/PS1 transgenic mice in the placebo control group." (PMID 35983247, 2022). "Collectively, these data showed that TS treatment was effective in reducing the production of Aβ and formation of senile plaques in the brain of APP/PS1 mice." (PMID 35935875, 2022). "The results showed that intervention with the CD38 inhibitor decreased the number of senile plaques in the hippocampus and cortex of APP/PS1 mice compared to the model group, and the accumulation of Iba1 + microglia decreased." (PMID 35241173, 2022). "The results showed that the entanglement of nerve fibers and senile plaques in the hippocampal tissues of APP/PS1 mice was significantly elevated, and meanwhile, consistent results were noted in APP/PS1/TRPML1+/+ mice in the presence of XRK3F2." (PMID 35116093, 2022). "RSV administered orally to APP/PS1 mice for 2 months (from the age of 4 months) reduced both senile plaques and oxidative stress responses compared with untreated mice." (PMID 35052635, 2022). "The APP is the precursor of a 40-42 amino acid peptide called amyloid-β-peptide (Aβ), that forms the central core of senile plaques." (PMID 36339406, 2022). "Amyloid β peptide (Aβ), derived from the amyloid precursor protein (APP), is the main component of senile plaques." (PMID 36683852, 2022). "The amyloid, also termed senile plaques (SPs), is mainly composed of proteinaceous components called Aβ peptides, which are formed by the cleavage of the large amyloid precursor protein (APP)." (PMID 35326204, 2022). "Extracellular senile plaques, one of the main characteristics of AD, are deposits of amyloid beta (Aβ) that arise from abnormal sequential cleavage of amyloid precursor protein (APP)." (PMID 34114603, 2021). "The site-directed redox activity of copper can produce APP fragmentation and promote Aβ aggregation, therefore contributing to the formation of senile plaques." (PMID 34202166, 2021). "Aβ, the main component of senile plaques found in the brains of AD patients, derives from a larger molecule known as the amyloid precursor protein (APP)." (PMID 34439505, 2021).
Senile plaques (continued). "AC-YVAD-CMK treatment improved spatial learning and memory ability and reduced senile plaque deposition of APP/PS1 mice." (PMID 33509083, 2021). "Above examination on APP/PS1 mice revealed that elevation of AEP is an early sign of AD pathology that precedes formation of senile plaques." (PMID 34412639, 2021). "In particular, the role of the amyloid precursor protein (APP) plays a crucial role in the formation of senile plaques and aging-dependent degeneration." (PMID 34209883, 2021). "AD is manifested either in a familial or sporadic form; the familial form is characterized by mutations in the amyloid precursor protein (APP) and presenilin 1 and 2, resulting in elevated levels of Aβ deposits and senile plaques." (PMID 32075060, 2020). "Results obtained in this study confirmed that genetic depletion of P2X7R leads to a significant reduction in the number of senile plaques in 10-months-old APP/PS1 mice." (PMID 32581707, 2020). "Senile plaques are characterized by the abnormal accumulation of amyloid β-peptide (Aβ), derived from the metabolism of the larger amyloid precursor protein, APP, abundantly expressed in platelets which process APP through the same pathways as in the brain." (PMID 32829706, 2020). "We also previously observed that APP/PS1xdb/db mice exhibit a shift in the kinetics of Aβ deposition, and while more toxic soluble Aβ species are increased, insoluble Aβ and senile plaques are reduced." (PMID 31992349, 2020). "Aβ, produced by hydrolysis of amyloid precursor protein (APP), is a major component of senile plaques and is considered to be a major pathological change in AD." (PMID 32180703, 2020). "This is significant as β-secretase (as well as γ-secretase) cleaves Amyloid Precursor Protein (APP) in a way that leads to neuropathologies in AD such as senile plaques, neuroplasticity deficits, and tau hyperphosphorylation." (PMID 31133796, 2019). "Amyloid precursor protein (APP), a transmembrane glycoprotein, is the parent of Abeta, the major component of senile plaques in AD." (PMID 31448273, 2019). "It was anticipated that APP and Aβ, the main components of senile plaques, would also occur in pure spirochetal biofilms, and that bacterial DNA and bacterial amyloid are important components of biofilms in senile plaques." (PMID 30250480, 2018). "In particular, senile plaques are formed by the deposition of a protein fragment called amyloid beta (Aβ), which derives from the cleaved products of amyloid precursor protein (APP)." (PMID 29992725, 2018). "Amyloid β (Aβ), a major component of senile plaques, is known to be cleaved from its precursor protein Amyloid precursor protein (APP) and secreted extracellularly." (PMID 30355327, 2018). "High iron content is loaded around senile plaques and elevates the production of Aβ by increasing the expression of amyloid-β precursor protein (APP)." (PMID 29114205, 2017). "Our results showed that BJJS treatment decreased the amyloid-β generation and the number of senile plaques in the brain of APP/PS1 mice." (PMID 29190943, 2017). "Accumulating evidences have shown that 9-month-old APP/PS1 transgenic mice exhibited the formation of senile plaques which gradually increased with age." (PMID 28337142, 2017). "What's more, the number of senile plaques was significantly decreased in the brain of high-dose BJJS group compared with the APP/PS1 group (P<0.01 vs. APP/PS1)." (PMID 29190943, 2017). "The γ-secretase enzyme acts on the Amyloid Precursor Protein (APP) membrane protein to produce the Aβ1–40 and Aβ1–42 fragments that are found in senile plaques." (PMID 28970891, 2017). "The amyloid precursor protein (APP), which undergoes cleavage to form amyloid-beta, and is aggregated in senile plaques in AD, is transported within axons via the molecular motor kinesin-1." (PMID 27213408, 2016).
Senile plaques (continued). "Several studies have demonstrated presence of senile plaques (βA) and amyloid precursor protein (APP) in close proximity to the ischemic focus, suggesting a degree of convergence in the neuropathogenesis of cerebral ischemia and AD." (PMID 28066230, 2016). "The appearance of senile plaques on brain cortex for 7-month-old APP/PS1 transgenic mice has indicated an early intervention of EA." (PMID 27829865, 2016). "The amyloid precursor protein (APP) has been identified as precursor of Aβ-peptides, the main constituents of senile plaques." (PMID 27092780, 2016). "Amyloid plaques, also called senile plaques, result from the deposition of aggregated Aβ peptides, which can be naturally produced via sequential cleavages of amyloid precursor protein (APP) by the β- and γ-secretase." (PMID 27418961, 2016). "One of the main pathological features of AD is the presence in the brain of senile plaques mainly composed of aggregated β amyloid (Aβ), a derivative of the longer amyloid precursor protein (APP)." (PMID 28031886, 2015). "Several studies have demonstrated senile plaques (βA) and amyloid precursor protein (APP) in close proximity to the ischemic focus, suggesting a degree of convergence in the neuropathogenesis of CI and AD." (PMID 26042033, 2015). "Amyloidogenic processing of APP by beta- and gamma-secretases generates Amyloid-beta (Abeta), the main component of senile plaques." (PMID 23776568, 2013). "The major component of senile plaques is amyloid-β-peptide (Aβ), a group of 39–43 amino acid peptides derived from the amyloid precursor protein (APP)." (PMID 24119446, 2013). "Aβ is formed from a larger protein named amyloid precursor protein (APP) via breakdown by the enzymes, α-, β- and γ-secretases, and deposited in extracellular plaques known as senile plaques." (PMID 24124514, 2013). "Similar to senile plaques, Aβ deposits are one of the pathological hallmarks of AD and Aβ generated from APP in the amyloidogenic pathway." (PMID 24194717, 2013). "AD is marked by senile plaques, which are extracellular inclusions of predominantly amyloid-β (Aβ) peptide derived from APP (amyloid precursor protein)." (PMID 22936898, 2012). "Earlier studies discovered that immunization of amyloid precursor protein (APP) in transgenic mice with Aβ reduced senile plaques and prevented new deposits of Aβ." (PMID 19582217, 2009). "According to this theory APP synthesis and or processing become abnormal due to a combination of genetic and environmental factors, which results in the formation of senile plaques." (PMID 19578515, 2008). "The morphology of senile plaques depends on the APP knock‐in mice brain fixative." (PMID 36879381, 2023). "Upon cleavage of the amyloid precursor protein (APP) by enzymes such as ⍺ and γ-secretins, a decreased or absent clearance of the Aβ product leads to their aggregation and the formation of APs, sometimes referred to as senile plaques." (PMID 37834345, 2023). "The first, senile plaques, are defined as extracellular aggregates of beta-amyloid protein (Aβ), which is produced through proteolytic cleavage of a critical membrane glycoprotein, amyloid precursor protein (APP)." (PMID 37426432, 2023). "Moreover, we were able to show a high ηCTF expression surrounding the core of abundant senile plaques in triple transgenic mice as was also shown in APP/PS1 transgenic mice and in AD brain." (PMID 36930302, 2023). "Moreover, pathological processing of amyloid precursor protein (APP) contributes to senile plaques (SPs) formation, with a consequential rise in free-radicals concentration and inflammation providing a hostile environment for neurons." (PMID 36397116, 2022). "Amyloid plaques (neuritic or senile plaques) are globular deposits composed of extracellular agglomerates of amyloid-β protein (Aβ) derived from improper cleavage of the amyloid precursor protein (APP)." (PMID 36421986, 2022).
Senile plaques (continued). "Moreover, trientine can significantly reduce the APP/presenilin-1 (PS1) mouse brain senile plaques and reduce copper and zinc accumulation in plaques." (PMID 34202166, 2021). "It is hypothesized that Alzheimer’s neuropathology is largely caused by the overexpression of the amyloid precursor protein (APP) located on chromosome 21 because APP produces amyloid ß protein, the main component of senile plaques." (PMID 34520978, 2021). "Great amounts of cortical and hippocampal senile plaques were observed in APP/PS1 control mice." (PMID 33291072, 2020). "Furthermore, semi-quantitative immunohistochemical analysis revealed that the number of senile plaques in the hippocampus of the APP/PS1 mice was significantly enhanced by either high- or lower-fluoride exposure." (PMID 31010414, 2019). "However, other studies demonstrated that intracerebrally transplanted human adipose MSCs activate microglia around senile plaques in the brain of APP/PS1 transgenic mice." (PMID 31057400, 2019). "Ginsenoside Rh2 could significantly improve learning and memory performance and reduce brain senile plaques at 14-month-old model mice through the reduction of amyloid beta (Aβ) secretion and amyloid precursor protein (APP) endocytosis." (PMID 31091790, 2019). "Another important gene, HNRNPA1 the human orthologue for sqd-1, is involved in alternative splicing of APP genes that could be targeted for reducing senile plaque formation." (PMID 31291334, 2019). "The APP/PS1 group had more bright green particles (senile plaques deposition) (P < 0.01)." (PMID 30079347, 2018). "Additionally, the number of senile plaques significantly decreased in the brain of high-dose BJJS group compared with the APP/PS1 group." (PMID 29190943, 2017). "Treatment with misoprostol significantly reversed the decrease of SOD activity and the increase of MDA content, decreased Aβ deposition and the number of senile plaques, reduced cerebral karyopycnosis and hyperchromatic nuclei and shortened the latency of APP/PS1 mice." (PMID 27015117, 2016). "Amyloid plaques, also known as “senile plaques”, originate from the amyloid beta (Aβ) peptide, following up its aberrant cleavage by β-secretase, of the transmembrane protein amyloid precursor protein (APP), whose function is unclear but thought to be involved in neuronal development." (PMID 27649135, 2016). "Aβ1-42, the metabolite of the APP and PS1 gene mutation, is a major component of senile plaques." (PMID 24447795, 2014). "Alzheimer's disease (AD) is a neurodegenerative disorder characterized pathologically by senile plaques, where the major constituent is the amyloid beta peptide (Aβ), a 39–43 amino acid peptide derived from proteolytic processing of amyloid precursor protein (APP)." (PMID 23675471, 2013). "A subsequent study by the same investigators found that the mRNA level of C3 in the cerebral cortex was 5-fold higher in APP/TGF-β1 mice than in APP mice at 2 months of age (prior to deposition of Aβ) and 2-fold higher at 12–15 months, when senile plaques are present." (PMID 15479474, 2004). "Additionally, Aβ peptides are one of the main components of senile plaques and key responsible for AD pathogenesis; Aβ peptides derive from the amyloidogenic metabolism of amyloid precursor protein (APP), which is present in neurons and glia as well as in other tissues." (PMID 37049607, 2023). "The hydrophobic peptide is secreted in the extracellular space after amyloid precursor protein (APP) proteolytic cleavage and distributed in various forms such as monomers, dimers, oligomers, protofibrils, and ultimately fibrils accumulation leads to formation of senile plaques." (PMID 35213966, 2022). "In AD, the major component of these protein aggregates present in senile plaques, is the amyloid beta (Aβ), a peptide of 39–42 amino acid residues which derives from the sequential proteolytic processing of the amyloid precursor protein (APP) by beta- and gamma-secretases." (PMID 24086258, 2013).